PMAIP1 (phorbol-12-myristate-13-acetate-induced protein 1)
Description:
Promotes activation of caspases and apoptosis. Promotes mitochondrial membrane changes and efflux of apoptogenic proteins from the mitochondria. Promotes proteasomal degradation of MCL1. Competes with BAK1 for binding to MCL1 and can displace BAK1 from its binding site on MCL1 (By similarity). Competes with BIM/BCL2L11 for binding to MCL1 and can displace BIM/BCL2L11 from its binding site on MCL1.
Synonyms: NOXA; APR
Tractability: PROTAC: ubiquitination databases record sites on it.
Gene: Protein-coding gene on chromosome 18 (59,899,644 to 59,904,305, forward strand). Ensembl gene ENSG00000141682.
Subcellular location: Mitochondrion
Subcellular location (Human Protein Atlas): Vesicles
Pathways (Reactome):
Programmed Cell Death: Activation of NOXA and translocation to mitochondria; BH3-only proteins associate with and inactivate anti-apoptotic BCL-2 members
Gene Ontology:
Molecular function: protein binding
Biological process: apoptotic process; cellular response to glucose starvation; cellular response to hypoxia; defense response to virus; intrinsic apoptotic signaling pathway; positive regulation of apoptotic process; positive regulation of extrinsic apoptotic signaling pathway via death domain receptors; positive regulation of glucose metabolic process; positive regulation of intrinsic apoptotic signaling pathway; positive regulation of release of cytochrome c from mitochondria; proteasomal protein catabolic process; reactive oxygen species metabolic process; regulation of mitochondrial membrane permeability; response to dsRNA; negative regulation of mitochondrial membrane potential; positive regulation of endoplasmic reticulum stress-induced intrinsic apoptotic signaling pathway; T cell homeostasis; DNA damage response; release of cytochrome c from mitochondria
Cellular component: Bcl-2 family protein complex; cytosol; mitochondrion; nucleus; mitochondrial outer membrane
Genetic constraint (gnomAD): Loss-of-function variants: 4 observed, 3.79 expected, observed/expected ratio (o/e) 1.06, 90% interval 0.5 to 1.86. That is too few expected variants to judge how well the gene tolerates losing a copy. Missense variants: 77 observed, 61 expected, observed/expected ratio (o/e) 1.26, 90% interval 1.05 to 1.53. Synonymous variants: 29 observed, 23.02 expected, observed/expected ratio (o/e) 1.26, 90% interval 0.94 to 1.71.
Homologues: Orthologues: dog PMAIP1 (83% identical), guinea pig Pmaip1 (72% identical), rabbit PMAIP1 (72% identical), mouse Pmaip1 (67% identical), pig PMAIP1 (67% identical), rat Pmaip1 (67% identical).
Diseases named in the same sentence as PMAIP1 in open-access papers:
PMAIP1 is named in the same sentence as 108 diseases in open-access papers, as found by Europe PMC text mining. Sharing a sentence is not in itself a finding about the gene and the disease. The quoted sentences say what the papers report.
melanoma (41 papers, 2008 to 2025). A malignant, usually aggressive tumor composed of atypical, neoplastic melanocytes. "Mechanistically, d-penicillamine-induced expression of phorbol-12-myristate-13-acetate-induced protein 1 (PMAIP1), encoding NOXA was necessary for melanoma cell death, as verified by knockdown experiments." (PMID 39970778, 2025). "The apoptosis of melanoma is induced by DMAS by upregulating phorbol-12-myristate-13-acetate-induced protein 1 (NOXA), and DMAS blocks hepatocellular carcinoma cell cycle arrest in the G2 phase." (PMID 36072666, 2022). "Copper chelating active substance (e.g., D-penicillamine) induce phorbol-12-myristate-13-acetate-induced protein 1 (PMAIP1) expression, which upregulates NOXA protein, a necessary condition for melanoma cell death, highlighting the potential of targeting copper homeostasis as a therapeutic strategy." (PMID 41170386, 2025).
breast cancer (30 papers, 2012 to 2025). A primary or metastatic malignant neoplasm involving the breast. "Earlier studies, by integrating multiomics analyses and experimental validation, have indicated that PMAIP1 may play a role in regulating glucose metabolism, thus affecting the tumor microenvironment in breast cancer." (PMID 41323776, 2025). "Western-blot analysis revealed that the protein expression of FBXO6, PMAIP1, ERP27, and CHAC1were significantly higher in breast cancer cell lines(SKBR-3, MDA-MB-231, T-47D)than in normal mammary epithelial cell line MCF-10A." (PMID 37313465, 2023). "Using multivariate Cox analysis, FBXO6, PMAIP1, ERP27, and CHAC1 were identified as independent prognostic factors in patients with breast cancer." (PMID 37313465, 2023). "We set out to investigate the effect of NAC on the expression of the NOXA gene, phorbol-12-myristate-13-acetate-induced protein 1 (PAMIP1), in breast cancer tissue." (PMID 37741850, 2023). "For example, FBXO6 expression did not significantly differ with breast cancer stage, while PMAIP1 expression was lower in late stages." (PMID 37313465, 2023).
lung carcinoma (28 papers, 2010 to 2026). "Pmaip1, a pro-apoptotic protein, has been reported to be associated with the apoptotic induction of various cancer cells, such as spinal cord glioma cells, lung cancer cells and mantle cell lymphoma." (PMID 41008561, 2025). "To summarize, the apoptosis induced by PTL in lung cancer cells is via both intrinsic and extrinsic apoptotic pathways, the intrinsic apoptosis is mediated through PMAIP1/MCL1 axis." (PMID 24387758, 2014). "Additionally, CTSV, which plays a role in apoptosis and lung cancer metastasis, and PMAIP1, a key pro-apoptotic regulator, showed significantly elevated expression in the treatment group." (PMID 40143009, 2025).
multiple myeloma (19 papers, 2008 to 2024). "The cytotoxicity of BZM in primary MCL, multiple myeloma and other neoplastic cells has been associated with pro-apoptotic phorbol-12-myristate-13-acetate-induced protein 1 (PMAIP1/Noxa) expression." (PMID 25714012, 2015). "The ability of a new Gal-3 antagonist, GCS-100, to induce myeloma cell death by modulating MCL1 apoptosis regulator BCL2 family member (MCL-1), phorbol-12-myristate-13-acetate-induced protein 1 (NOXA), and the cell cycle was assessed in the U266 and RPMI 8226 cell lines." (PMID 36364232, 2022).
leukemia (17 papers, 2010 to 2025). A malignant (clonal) hematologic disorder, involving hematopoietic stem cells and characterized by the presence of primitive or atypical myeloid or lymphoid cells in the bone marrow and the blood. "Studies have confirmed the involvement of PMAIP1 in leukemia, pancreatic cancer, pituitary adenoma and triple-negative breast cancer, and other cancer types." (PMID 40476267, 2025).
lymphoma (17 papers, 2011 to 2025). A malignant (clonal) proliferation of B- lymphocytes or T- lymphocytes which involves the lymph nodes, bone marrow and/or extranodal sites. "Eμ-Myc lymphoma cells treated with M-100 de-repressed Bbc3 as well as Pmaip1 and repressed Bcl2 expression." (PMID 36068335, 2022). "Gene expression of Bbc3 and Pmaip1, encoding pro-apoptotic Puma and Noxa was increased in lymphoma but not wild-type B-cells after M-100 treatment." (PMID 36068335, 2022). "In addition, we showed that both BCL2L11 and PMAIP1 were downregulated by the tumor microenvironment in all the B-cell malignancies studied (MCL, FL, CLL, and SMZL), suggesting a fundamental role of these 2 specific BH3-only proteins in the microenvironment-dependent survival of lymphoma cells." (PMID 30666297, 2018).
neuroblastoma (17 papers, 2008 to 2025). Neuroblastoma (NB) is the most common solid, extracranial childhood tumor. "FOXO3 triggers apoptosis via upregulation of the proapoptotic BH3-only proteins BIM and PMAIP1/NOXA in neuroblastoma cells." (PMID 28545464, 2017). "This analysis uncovered the MCL-1 inhibitor NOXA, encoded by PMAIP1, to be significantly higher in MYCN-amplified neuroblastomas." (PMID 26859456, 2016). "The relationship between MYCN and PMAIP1 expression in MYCN-amplified neuroblastoma cells was significant, raising the possibility that MYCN may regulate PMAIP1 in these tumors." (PMID 26859456, 2016). "Further analysis demonstrated that the Mcl-1 inhibitor NOXA, encoded by PMAIP1, was significantly higher in N-Myc amplified neuroblastomas suggesting that increased NOXA expression was a contributing factor to ABT-199 sensitivity observed in N-Myc amplified neuroblastoma cells." (PMID 30885150, 2019). "As in the PDAC context, where MYC directly activates the transcription of the pro‐death BCL2 family member NOXA (PMAIP1) upon bortezomib treatment, NOXA contributes also in neuroblastoma models significantly to the bortezomib‐induced apoptosis." (PMID 33099868, 2020). "In neuroblastoma cells, FOXO3 regulates cellular apoptosis by activating the two BH3-only proteins PMAIP1/Noxa and BCL2L11/Bim and sensitizes these tumor cells to chemotherapy-induced cell death by repressing the IAP-family member BIRC5/Survivin." (PMID 25261981, 2014). "The positive relationship between PMAIP1 mRNA expression and MYCN mRNA expression was also observed in a large collection of neuroblastoma cell lines and confirmed in our neuroblastoma cell line panel." (PMID 26859456, 2016). "High expression of PMAIP1 in the subset of MYCN-amplified neuroblastomas was confirmed in a second dataset of neuroblastomas, again without differential expression of other key BCL-2 family members." (PMID 26859456, 2016).
pancreatic cancer (16 papers, 2008 to 2025). "Research indicated that NOXA/PMAIP1 serves as a marker for an aggressive subtype of pancreatic ductal adenocarcinoma, with NOXA/PMAIP1 expression inducing synthetic lethality upon RUNX1 inhibition in pancreatic cancer." (PMID 39944827, 2025). "PMAIP1 upregulation together with downregulation of the anti-apoptotic BCL2L1 protein have been correlated with increased apoptosis in pancreatic tumor cells treated with an oleanolic acid derivative." (PMID 27589063, 2016). "PMAIP1 is a crucial gene for the activation of caspases and apoptosis; it has been identified as a candidate tumour suppressor gene that is frequently downregulated in pancreatic cancer." (PMID 32958051, 2020).
colorectal cancer (13 papers, 2017 to 2025). A primary or metastatic malignant neoplasm that affects the colon or rectum. "For example, CBD can trigger Noxa (Pmaip1) mediated apoptosis in colorectal cancer cells in a dose dependent manner (0–8 μM) by generating ROS and inducing excessive endoplasmic reticulum (ER) stress, mainly driven by mitochondrial superoxide anion." (PMID 39289171, 2024). "Additionally, a study involving 160 patients with colorectal cancer and adjacent tissues demonstrated that NOXA/PMAIP1 was overexpressed in colorectal cancer tumors, even at early stages." (PMID 39944827, 2025). "PMAIP1 is involved in the intrinsic apoptosis pathway, selectively binds to MCL1, and prevents MCL1 to inhibiting apoptosis in colorectal cancer." (PMID 33506057, 2021).
acute myeloid leukemia (7 papers, 2017 to 2025). Acute myeloid leukemia (AML) is a group of neoplasms arising from precursor cells committed to the myeloid cell-line differentiation. "Prior research has indicated that azacitidine has the ability to enhance the expression of PMAIP1, leading to heightened sensitivity of preclinical acute myeloid leukemia models to venetoclax." (PMID 40476267, 2025). "This combination, through the ISR-mediated induction of PMAIP1, could reduce drug resistance in acute myeloid leukemia." (PMID 39944827, 2025). "Similarly, the downregulation of BAX and Phorbol-12-myristate-13-acetate-induced protein 1 (NOXA), other pro-apoptotic proteins, has been linked to resistance in acute myeloid leukemia (AML)." (PMID 39757310, 2025). "Furthermore, azacitidine was observed to upregulate the expression of PMAIP1, thereby enhancing the sensitivity of preclinical models of acute myeloid leukemia to venetoclax." (PMID 39944827, 2025).
head and neck squamous cell carcinoma (7 papers, 2012 to 2024). A squamous cell carcinoma that arises from any of the following anatomic sites: lip and oral cavity, nasal cavity, paranasal sinuses, pharynx, larynx, and salivary glands. "That suggestion was supported by another study in which cisplatin-induced ATF3 in head and neck squamous cell carcinoma cells resulted in induction of apoptosis accompanied by an increased level of PMAIP1 through cooperative binding of ATF3 and ATF4 to the PMAIP1 promoter." (PMID 31296259, 2019).
non-small cell lung carcinoma (7 papers, 2019 to 2026). A group of at least three distinct histological types of lung cancer, including non-small cell squamous cell carcinoma, adenocarcinoma, and large cell carcinoma. "AP-2γ inhibits GADD45B expression, with overexpressed TFAP2C suppressing GADD45B and PMAIP1 at both mRNA and protein levels in non-small cell lung cancer cells." (PMID 41373739, 2025).
Obesity (7 papers, 2015 to 2025). Accumulation of substantial excess body fat. "For example, LRPPRC is involved in cytoskeletal regulation and bone development, PMAIP1 is associated with obesity, and PPP1R11 has roles in cell proliferation and fat metabolism." (PMID 40630222, 2025). "PMAIP1 has been reported to be associated with obesity, body mass index (BMI), and height in humans and average daily gain (ADG) in pigs, while DENND2A has been proposed as a candidate gene for BFT." (PMID 39932890, 2025). "Other candidate genes which have been reported in humans, for example, the PMAIP1 and UBE2E2 genes are involved in human obesity." (PMID 37407918, 2023). "Moreover, STAT3, MCL1, PMAIP1, SOD2, FOXO3, FOS, FKBP5 may play an essential role in the genesis and growth of obesity and might serve as a possible therapeutic target." (PMID 34712134, 2021). "Additionally, other causal genes are highly expressed or known to act in human brain function (i.e., NEGR1, GNPDA2, CYP46A1, DGKH) and various carcinomas (i.e., PMAIP1, HORMAD1, FES, BCAS3), indicating the potential role of metabolic dysregulation in the pathogenesis of obesity and cardiac events." (PMID 33910581, 2021).
ovarian carcinoma (7 papers, 2012 to 2025). A malignant neoplasm originating from the surface ovarian epithelium. "In regard to the observed positive correlation of FAS and PMAIP1 with early follicular phase serum LH levels, LH has potential to protect cells against Fas-induced apoptosis as its protective effect has been reported in ovarian cancer HEY cells." (PMID 37468508, 2023). "PMAIP1 is related to the development of ovarian cancer and spinal cord glioma cells." (PMID 33613623, 2020).
triple-negative breast carcinoma (7 papers, 2019 to 2025). An invasive breast carcinoma which is negative for expression of estrogen receptor (ER), progesterone receptor (PR), and human epidermal growth factor receptor 2 (HER2). "PMAIP1 (NOXA) reportedly induces apoptosis as a BCL-53 family pro-apoptotic factor in triple-negative breast cancer." (PMID 37313465, 2023).
cervical cancer (6 papers, 2011 to 2023). A primary or metastatic malignant neoplasm involving the cervix. "It implies that ERs-related genes (ATF4 and DDIT3) and downstream apoptosis genes (JUN, FOS, BBC3, and PMAIP1) are the potential targets of 20(S)-GRh2 and might be interacting with each other to be involved in the apoptosis induction in cervical cancer cells." (PMID 36431966, 2022). "Combined protein–protein interaction network, hub gene screening, and qPCR validation data showed that ERs-related genes (ATF4 and DDIT3) and the downstream apoptotic genes (JUN, FOS, BBC3, and PMAIP1) were potential novel targets of 20(S)-GRh2-inducing cervical cancer cell apoptosis." (PMID 36431966, 2022).
acute lymphoblastic leukemia (4 papers, 2018 to 2025). Leukemia with an acute onset, characterized by the presence of lymphoblasts in the bone marrow and the peripheral blood.
viral infection (4 papers, 2020 to 2022). "It is relevant to consider that MSC are usually resistant to viral infection due to their expression of interferon (IFN), and, subsequently, IFN-stimulated genes (ISGs) (such as IFI6, ISG15, SAT1, PMAIP1, p21/CDKN1A, and CCL2)." (PMID 33808241, 2021). "Interestingly, MSC are usually resistant to viral infection due to their expression of ISGs such as IFITM, IFI6, ISG15, SAT1, PMAIP1, p21/CDKN1A, and CCL2 that preempt viral infection." (PMID 33808241, 2021). "Interestingly, MSC are usually resistant to viral infection due to their expression of interferon (IFN) stimulated genes (ISG) such as IFITM (interferon-induced transmembrane family), IFI6, ISG15, SAT1, PMAIP1, p21/CDKN1A, and CCL2 that preempt viral infection." (PMID 32766251, 2020).
breast tumors (3 papers, 2011 to 2023). "In contrast, other breast tumors appeared statistically enriched for two PMAIP1 (Noxa) specific probes and for one BAD specific one." (PMID 21899728, 2011). "We compared the expression profiles of 272 ERS-related genes in primary breast tumors and normal breast tissue and identified FBXO6, PMAIP1, ERP27, and CHAC1 as independent prognostic factors with established risk models (defining the risk scores as ERScore) and model validation." (PMID 37313465, 2023).
follicular thyroid carcinoma (3 papers, 2025). "Furthermore, research has shown that PMAIP1 influences the development of follicular thyroid carcinoma through the Wnt3/FOSL1 signaling pathway." (PMID 41323776, 2025).
gastric cancer (3 papers, 2017 to 2025). A primary or metastatic malignant neoplasm involving the stomach. "Another study demonstrated that PMAIP1 mRNA can be targeted by miR-21 in gastric carcinoma, resulting in the inhibition of proliferation, invasion, and migration." (PMID 31296259, 2019).